PPP3R2 (protein phosphatase 3 regulatory subunit B, beta)
Description:
Regulatory subunit of calcineurin, a calcium-dependent, calmodulin stimulated protein phosphatase. Confers calcium sensitivity.
Synonyms: PPP3RL
Tractability: Antibody: the Human Protein Atlas places it where antibodies can reach. PROTAC: ubiquitination databases record sites on it.
Gene: Protein-coding gene on chromosome 9 (101,591,604 to 101,595,021, reverse strand). Ensembl gene ENSG00000188386.
Subcellular location: Mitochondrion
Subcellular location (Human Protein Atlas): Plasma membrane; Cytosol; Primary cilium
Gene Ontology:
Molecular function: calcium-dependent protein serine/threonine phosphatase regulator activity; protein binding; phosphatase binding; calcium ion binding
Biological process: calcineurin-mediated signaling; negative regulation of calcium ion import across plasma membrane; positive regulation of calcineurin-NFAT signaling cascade; positive regulation of calcium ion import across plasma membrane
Cellular component: calcineurin complex; cytosol; mitochondrion; protein serine/threonine phosphatase complex; sperm flagellum; sperm midpiece; sperm mitochondrial sheath
Genetic constraint (gnomAD): Loss-of-function variants: 1 observed, 2.5 expected, observed/expected ratio (o/e) 0.4, 90% interval 0.14 to 1.62. That is too few expected variants to judge how well the gene tolerates losing a copy. Missense variants: 225 observed, 230.33 expected, observed/expected ratio (o/e) 0.98, 90% interval 0.88 to 1.09. Synonymous variants: 91 observed, 96.58 expected, observed/expected ratio (o/e) 0.94, 90% interval 0.79 to 1.12.
Homologues: Orthologues: rat Ppp3r2 (83% identical), mouse Ppp3r2 (81% identical), Caenorhabditis elegans chpf-2 (39% identical), Caenorhabditis elegans chpf-1 (38% identical), Drosophila melanogaster elm (36% identical), Drosophila melanogaster Cib2 (33% identical), Caenorhabditis elegans calm-1 (31% identical), Drosophila melanogaster CG14362 (26% identical), Drosophila melanogaster CG32812 (22% identical). Paralogues in human: PPP3R1 (84% identical), CHP1 (42% identical), CHP2 (36% identical), TESC (29% identical), CIB1 (28% identical), CIB2 (28% identical), CIB3 (27% identical), CIB4 (26% identical).
Diseases named in the same sentence as PPP3R2 in open-access papers:
PPP3R2 is named in the same sentence as 6 diseases in open-access papers, as found by Europe PMC text mining. Sharing a sentence is not in itself a finding about the gene and the disease. The quoted sentences say what the papers report.
Infertility (2 papers, 2024 to 2025). "A lack of PPP3R2 resulted in decreased motility and eventual infertility in male mice." (PMID 38246484, 2024).
male infertility (2 papers, 2016 to 2025). The inability of the male to effect fertilization of an ovum after a specified period of unprotected intercourse. "Sperm-specific calcineurin consists of a catalytic subunit (PPP3CC) and a regulatory subunit (PPP3R2), and the deletion of PPP3CC/PPP3R2 resulted in male infertility due to an inflexible mid-piece of sperm in mice." (PMID 41428164, 2025). "Next, to clarify the specific contribution of FKBP12.6 in FK506-induced male infertility, we prepared several tagged proteins including GST-tagged FKBP12, GST-tagged FKBP12.6, His-tagged PPP3CC, and His-tagged PPP3R2, for conducting the pull-down experiments." (PMID 41428164, 2025).
PPP3R2 also shares sentences with these, for which no sentence is quoted: cancer (1 paper); muscular dystrophy (1); Obesity (1); osteoarthritis (1).